MICA (MHC class I polypeptide-related sequence A)
Diseases named in the same sentence as MICA in open-access papers (continued):
Sharing a sentence is not in itself a finding about the gene and the disease.
Autoimmunity (12 papers, 2009 to 2021). The occurrence of an immune reaction against the organism's own cells or tissues. "Previous association studies have shown a link of polymorphism of MICA/B and/or alteration in sMICA/B to cancers, autoimmunity and host-graft reaction." (PMID 23181907, 2012). "Disease association studies focusing on the MICA-129 Met/Val dimorphism suggest a complex role in the immune system in which the high affinity allele MICA-129 Met is associated with strong immune activation, reducing the likelihood of infections or cancer but also stimulating autoimmunity." (PMID 29867932, 2018). "We have previously noted that localized tissue expression of MICA and IL-15 can lead to autoimmunity mediated by CD8+ effector T cells, likely due to the capability of IL-15 to drive the expression of NKG2D and activate its cytolytic pathway." (PMID 24086722, 2013). "Beyond its value for basic cell biology, discovering MICA*008’s maturation pathway may open possibilities for manipulating the expression of this common immune ligand, involved in autoimmunity, graft rejection, and cancer." (PMID 33824318, 2021). "For example, although MICA is expressed at a low level by healthy intestinal epithelial cells (IECs), patients with Crohn’s Disease demonstrate increased MICA expression on these IECs compared to healthy controls, leading to activation and autoimmunity from a subset of CD4+NKG2D+ T cells." (PMID 33352921, 2020). "Thus, the interaction between NKG2D and MICA‐129 may potentially increase the risk of disease by increasing the production of cytokines by NK cells and may also promote costimulatory signalling of CD8+ T cells in autoimmunity." (PMID 33017098, 2020). "It has been hypothesised that these miRNAs play a critical part in the regulation of MICA and MICB protein expression and preventing unwanted autoimmunity." (PMID 33352921, 2020). "Elevated serum MICA and MICB were reported in cancer and autoimmune conditions." (PMID 26909604, 2016). "Hence, MICA expression is prone to a rapid recognition by NKG2D-bearing IELs, while ULBP1–3 and murine RAE-1 become available only in the event of epithelial polarity breaking, as result of infection or autoimmunity." (PMID 29209320, 2017).
glioma (12 papers, 2011 to 2023). A benign or malignant brain and spinal cord tumor that arises from glial cells (astrocytes, oligodendrocytes, ependymal cells). "Compared to other NKG2DLs, their discovery suggests that the loss of MICA and ULBP2 plays a more significant role in glioma immune escape." (PMID 37565867, 2023). "On the tumor side, TGF-β inhibits the transcription of the NKG2D ligands on tumor cells such as down regulation of MICA in the glioma cells, which reduced the recognition and killing by NKG2D expressing NK." (PMID 30805309, 2019). "The increase of MICA/B levels subsequently enhanced the recognition and killing of glioma cells by NK-cells." (PMID 29867351, 2018). "At the immunofluorescence analysis, a weak MICA expression was detected on untreated glioma GBM17 cells while, of course, it was much higher after 24 h treatment with SR141716." (PMID 26008966, 2015). "Indeed, SR141716 impacts U251 and primary glioma cells growth and MICA/B expression through the specific inhibition of activated STAT3, a transcription factor harboring both oncogenic and immunosuppressive functions." (PMID 26008966, 2015). "Then, it was still important to verify the functionality of MICA/B and further investigate if the SR141716-dependent increase in MICA/B expression could enhance NK cell recognition and killing of U251 glioma cells." (PMID 26008966, 2015). "We and others have reported previously that engagement of MICA/B with NKG2D present on Vγ2Vδ2 T cells resulted in a substantial enhancement of TCR-dependent T cell response to nonpeptide antigens and protein superantigens alike in various pathogenic infections and gliomas." (PMID 21935360, 2011). "For example, in vitro silencing of TGF-β1 and TGF-β2 synthesis in human glioma cells using small interfering RNA (siRNA) techniques was shown to prevent NKG2D down-regulation on NK cells and enhance MICA expression on glioma cells." (PMID 26217588, 2015). "Previous studies and our data demonstrated that most gliomas expressed MICA and ULBP proteins, but not MICB." (PMID 31288857, 2019). "Interestingly however, SR141716 additionally upregulated the expression of NKG2D ligands (MICA and MICB) on the surface of glioma cells via STAT3 inactivation." (PMID 29867351, 2018). "Indeed, in addition to the direct cytotoxic and antiproliferative effect in established U251 glioma cell line and primary tumor cells, SR141716 also improves the immunorecognition of cancer cells by inducing the NKG2D ligand MICA/B." (PMID 26008966, 2015). "First, we monitored by flow cytometry the cell surface expression of the NKG2D ligand MICA, MICB, ULBP1, ULBP2, ULBP3, ULBP4 and MHC class I on untreated and SR141716-treated U251 glioma cells at 24 h to exclude that the possibility of observed effects are linked to the stress of dying cells." (PMID 26008966, 2015). "Of note, MICA/B-blocking mAbs didn't affect basal cell lysis, indicating that constitutive NK cell degranulation and U251 glioma cell lysis probably does not involve NKG2D activating receptor." (PMID 26008966, 2015). "Furthermore, although TGF-β signalling increases metalloproteinase expression on glioma cells, the increased shedding of MICA and ULBP2 by glioma cells was not due to TGF-β-dependent metalloproteinases." (PMID 33352921, 2020). "According to the findings on U251 glioma cell line, SR141716 increases the expression of MICA on the responsive high-CB1-expressing cells, but not on low-CB1-expressing primary cell lines." (PMID 26008966, 2015).
osteosarcoma (12 papers, 2016 to 2025). A usually aggressive malignant bone-forming mesenchymal neoplasm, predominantly affecting adolescents and young adults. "Hsa-miR-711, which may regulate MICA expression on patients carrying UTR1a and UTR2c, has been associated with osteosarcoma-associated proliferation, migration, and invasion; it is regulated by circular RNA circ_0008792." (PMID 38146340, 2023). "Both ULPB1 and MICA/MICB transcripts are significantly (p < 0.01) upregulated in osteosarcoma tissues compared to normal tissues, suggesting enhanced baseline stress levels in osteosarcoma tumor cells due to their malignant nature." (PMID 40969756, 2025). "The human osteosarcoma cell lines U-2 OS, 143B, and Mg63 highly expressed MICA/B and CXCL13, thus presenting a perfect avenue for the present study." (PMID 39450160, 2024). "In osteosarcoma patients, a deficiency of MICA–NKG2D-mediated immunesurveillance is revealed by prevalent expression of MICA and higher serum level of soluble MICA." (PMID 27683579, 2016). "In addition, the proteolytic activity of MMP-9 in osteosarcoma induced the cleavage of MICA on the surface of cancer cells." (PMID 34502191, 2021). "Given the high expression of MICA/B and CXCL13, human osteosarcoma cell lines constitute the perfect avenue for studying our CAR system expressing NKG2D, CXCR5, and IL-7." (PMID 39450160, 2024). "Interestingly, some NKG2D ligands (MICA, MICB, ULBP-2 and ULBP-3) are secreted from NSCLC, osteosarcomas and gastric cancer cells and may be shed by MMP-mediated cleavage." (PMID 34638439, 2021).
prostate carcinoma (11 papers, 2008 to 2025). A carcinoma that arises from epithelial cells of the prostate gland. "Research revealed that PTS boosts the susceptibility of prostate cancer cells to NK cell-mediated cytotoxicity by upregulating MICA/B (MHC Class I Chain-Related Proteins A and B) expression, which are ligands for NKG2D, and reducing TGF-β1 secretion through the inhibition of miR-20a." (PMID 41226811, 2025). "Additional cancer-associated genes affected by promoter-associated risk alleles include CLIC1, which facilitates prostate cancer proliferation and migration; MICA, which enhances immune evasion mechanisms; and UHRF1 BP1, which supports prostate tumor progression through epigenetic regulation." (PMID 41468516, 2025). "Interestingly, prostate cancer cell line PC-3 was the only cell type that upregulated MICA in response to HC." (PMID 32849657, 2020). "We observed that CD155 and CD112 were expressed at higher levels than MICA, MICB, ULBP1-2-5-6, PDL-1, and B7-H6 on all the prostate cancer cells (∗∗∗p < 0.001)." (PMID 35465350, 2022). "Since tumor cells are recognized by NK cells through an interplay of activating and inhibitory ligands, we decided to evaluate the expression of CD155, CD112, MICA, MICB, ULBP1-2-5-6, PDL-1, and B7-H6 on 22Rv1, LNCaP, and DU145 prostate cancer cells." (PMID 35465350, 2022). "MICA downregulation related to shedding under hypoxia, as well as downregulated expression of NKG2D on PBMCs incubated with culture supernatants of prostate cancer cells exposed to hypoxia—abrogated upon incubation with MICA blocking antibodies—has been reported." (PMID 29963058, 2018). "Furthermore, interfering with the hypoxia-induced accumulation of HIF-1α and ADAM10 has been shown to enhance MICA surface expression and to reduce MICA shedding, leading to augmented cytotoxicity of PBL against DU145 prostate cancer cells under hypoxia." (PMID 23724099, 2013). "Since OPM-1 expressed low levels of MICA, it is possible that, in contrast to the prostate cancer cells, MICA is not shed by OPM-1 cells." (PMID 23724099, 2013).
systemic lupus erythematosus (11 papers, 2009 to 2024). An autoimmune multi-organ disease typically associated with vasculopathy and autoantibody production. "In conclusion, sMICA concentrations are elevated in SLE patients, whereas plasma membrane MICA is up-regulated in response to some lupus stimuli and triggers NK cell activation." (PMID 34012432, 2021). "The emergence of graft-versus-host disease and systemic lupus erythematosus (SLE) is attributed to the processes of NK cell-mediated cytotoxicity and the production of immunosuppressive soluble MICA (sMICA) particles." (PMID 38474281, 2024). "In fact, anti-MICA autoantibodies have been described in early-onset systemic lupus erythematosus (SLE)." (PMID 24565339, 2014). "In this study we analyzed for the first time eight polymorphisms of microsatellite loci at the HLA region: D6S291, D6S273, TNFa, b and c, MICA, D6S265 and D6S276, in Tunisian systemic lupus erythematosus (SLE) patients." (PMID 29912900, 2018). "The lack of and/or failure to induce MICA/B and/or ULBP1 in jSLE monocytes is consistent with current concepts of lupus-related myeloid cell abnormalities." (PMID 28944101, 2017).
Behçet's disease (10 papers, 2012 to 2024). "More recently, a robust genetic association between a genetic variant between HLA-B and MICA was suggested to explain the association with HLA-B*51 in Behçet's disease." (PMID 33644100, 2021). "In particular, MICA polymorphisms are associated with inflammatory rheumatic diseases, Behçet’s disease, IBD1, systemic lupus and ankylosing spondylitis." (PMID 30177859, 2019). "Immunologically related studies such as those investigating Behçet's disease also found a positive association between MICA*009 and disease development." (PMID 25838620, 2015). "Similarly, studies in Turkey and Saudi Arabia confirmed HLA-B*51:01 as a predominant genetic marker in BD patients Greek research identified the involvement of the MICA-TM A6 allele and HLA-B*51:01 in Behçet's Disease within a European population." (PMID 38575661, 2024). "Finally, a recently published analysis of imputed genome wide association study data described an association between a genetic variant located between the HLA-B and MICA loci and Behçet’s disease." (PMID 25889603, 2015). "However, in these studies a relationship between HLA-B*51 and Behçet's disease was also reported, suggesting that the observed association between MICA*009 and Behçet's disease arises from a strong linkage disequilibrium with HLA-B*51." (PMID 25838620, 2015). "However, whether the classical allele HLA-B*51 or the HLA-B/MICA intergenic locus is causal in Behçet's disease requires further investigation." (PMID 33644100, 2021). "Although the relationships between NKG2D and MICA polymorphisms associated with autoimmune and neoplastic diseases, including ankylosing spondylitis, Behçet's disease, psoriasis vulgaris, and Kawasaki's disease, have been defined, this is not the case for the association of MICA alleles with AITD." (PMID 23209462, 2012).
colon carcinoma (9 papers, 2012 to 2025). "We performed immunohistochemical staining (IHC) to assess MICA/B expression in a panel of 146 PDXs corresponding to different types of human cancer (breast, lung and colon cancer)." (PMID 35967081, 2021). "They found that microbially-produced metabolic propionate-induced Kac and Kpr upregulates major histocompatibility complex class I polypeptide-related sequence A and B (MICA/B) expression in colon cancer cells, thereby inhibiting the development of colon cancer." (PMID 38315203, 2024). "Oxidative stress has been shown toincrease MICA gene expression in a colon carcinoma cell line." (PMID 22475346, 2012). "BCL11B up-regulates NKG2D ligands of the major histocompatibility complex class I-related molecules A and B (MICA and MICB), promotes the anti-tumor response of T- and NK-cells and prevents immune evasion of colon cancer cells." (PMID 36600891, 2022).
glioblastoma (9 papers, 2018 to 2025). The most malignant astrocytic tumor (WHO grade IV). "Circular EZH2 is highly expressed in glioblastoma cells and encodes EZH2-92aa, which binds MICA/B promoters to suppress their expression and also represses ULBP transcription via stabilizing EZH2." (PMID 38933287, 2023). "In glioblastoma, radiation and the DNA alkylating agent, temozolomide, were shown to induce MICA, MICB, ULBP2, and ULBP3 ligand expression in vitro and in vivo, which conferred higher immunoreactivity." (PMID 35565467, 2022). "Most gliomas express MICA/B and ULBP proteins, and NKG2D CAR-T has recently been shown to be effective against glioblastoma." (PMID 39877353, 2024). "Three representative glioblastoma cell lines (U251, U87, A172) were selected for assessing cell surface expression of NKG2DL (MICA/B, ULBP1, ULBP2/5/6, ULBP3, and ULBP4) by flow cytometry." (PMID 39877353, 2024). "In a glioblastoma (GBM) model, the expression of MHC-I and -II, APM molecules and ligands of NKG2D (MHC class I–related chains A and B (MICA/B), UL16 binding proteins (ULBPs)) have been reported down-regulated or defective in CSCs." (PMID 33806296, 2021). "Cell surface expression of the main ligands for the NKG2D receptor (MICA, MICB, ULBP1, ULBP2, and ULBP3) on the glioblastoma cell lines, U-251MG, T98G, and U-87MG, was assessed by flow cytometry." (PMID 31288857, 2019). "Next, the co-expression of the glioblastoma stem cell marker NESTIN and NKG2DLs (MICA, MICB, ULBP1, ULBP2, ULBP3) in these suspended cell spheres was assessed by flow cytometry." (PMID 31288857, 2019). "In glioblastoma multiforme (GBM) patients, MICA and ULBP1 were detected on microglia, tumor-infiltrating myeloid cells, and circulating monocytes." (PMID 29740438, 2018). "Consequently, NKG2D ligands, containing MICA/B and ULBP, are down-regulated by EZH2-92aa in glioblastoma, which accounts for immune escape of glioblastoma to NK cells in clinical treatment." (PMID 38933287, 2023). "Additionally, temozolomide was able to induce multiple NKG2D ligands (MICA/B, ULBP1-3) in a glioblastoma stem cell model." (PMID 35565467, 2022). "MICA shedding is not a universal evasion mechanism employed by all cancer cells, however, as glioblastoma cell lines did not shed MICA, although this study was only carried out under normoxia." (PMID 29963058, 2018).
metastatic melanoma (9 papers, 2014 to 2022). A melanoma that has spread from its primary site to another anatomic site. "Using MICA as example of a tumour-derived antigen, endogenously expressed in metastatic melanoma and recruited to exosomes, we have developed two immunocapture-based assays for detection of different epitopes in nanovesicles." (PMID 29720199, 2018). "The relationship between MICA expression and metastasis had been observed with uveal melanoma where metastatic melanoma cells have lower MICA expression than primary tumors." (PMID 28154561, 2016). "Early reports showed the loss of MICA/B expression in metastatic melanoma suggesting the immune selection of MICA/B negative tumors." (PMID 24711808, 2014). "Serum CEACAM1, MICA and MICB concentrations were measured by ELISA in ∼50 subjects of each group: acute pericarditis (AP), recurrent pericarditis (RP) and lupus (SLE) patients, metastatic melanoma patients as well as healthy donors." (PMID 26909604, 2016). "MICA and MICB were strongly elevated in SLE patients and in patients with metastatic melanoma, irrespective of neoplastic pericardial involvement." (PMID 26909604, 2016).
liver cancer (8 papers, 2013 to 2026). An epithelial or non-epithelial malignant neoplasm that arises from the liver. "In conclusion, the current meta-analysis indicates that MICA rs2596542G>A polymorphism is associated with susceptibility to HCV-induced HCC, suggesting that MICA polymorphism plays an important role in HCV-associated liver cancer progression." (PMID 30967497, 2019). "The HDAC inhibitor MS-275 epigenetically modified exosomes secreted by human liver cancer cells, increasing the expression of MICA, MICB, and heat shock protein 70, and enhancing the cytotoxic effects of NK cells." (PMID 38915093, 2024). "Therefore, in the current study, we have tried to investigate whether the MICA variations would affect the MICA transcription in the liver cancer cells." (PMID 23593449, 2013).
non-small cell lung carcinoma (8 papers, 2017 to 2025). A group of at least three distinct histological types of lung cancer, including non-small cell squamous cell carcinoma, adenocarcinoma, and large cell carcinoma. "High-intensity MICA expression has been linked to reduced survival in non-small-cell lung cancer (NSCLC)." (PMID 37626965, 2023). "It has been previously demonstrated that the SNP rs9266825, which is part of MICA*002, *007, *018, *017, *001 alleles, is associated with increased survival rates in non-small cell lung cancer patients." (PMID 33868281, 2021). "Cisplatin was previously reported to induce the MICA and MICB expression in non-small-cell lung cancer A549 cell line, through DNA stress-induced ATM-ATR signalling, resulting in enhanced sensitivity to NK cell-mediated cytotoxicity." (PMID 29805983, 2018). "Furthermore, pathway analysis revealed an enrichment of genes co-expressed with MICA in Non-small cell lung cancer, Ras signaling pathway, MAPK signaling pathway, etc, indicating the important role of MICA in carcinogenesis process." (PMID 32010612, 2019). "MICA/B expression level may not be a useful prognostic indicator in gynecologic malignant tumors and non-small cell lung carcinoma." (PMID 29221214, 2017).